ARHGAP20 (Rho GTPase activating protein 20)
Description:
GTPase activator for the Rho-type GTPases by converting them to an inactive GDP-bound state.
Synonyms: KIAA1391; RARHOGAP
Tractability: Small molecule: a structure with a bound ligand is known.
Gene: Protein-coding gene on chromosome 11 (110,577,042 to 110,713,189, reverse strand). Ensembl gene ENSG00000137727.
Subcellular location (Human Protein Atlas): Mitochondria
Pathways (Reactome):
Signal Transduction: CDC42 GTPase cycle; RAC1 GTPase cycle; RHOA GTPase cycle
Gene Ontology:
Molecular function: GTPase activator activity
Biological process: regulation of small GTPase mediated signal transduction; regulation of Rho protein signal transduction; signal transduction
Cellular component: cytosol
Genetic constraint (gnomAD): Loss-of-function variants: 24 observed, 55.06 expected, observed/expected ratio (o/e) 0.44, 90% interval 0.31 to 0.61. The upper end of that interval is the gene's LOEUF score, 0.61, which puts it in group 2 of 6, group 1 being the genes least tolerant of losing a copy. Missense variants: 1,223 observed, 1,350.4 expected, observed/expected ratio (o/e) 0.91, 90% interval 0.86 to 0.95. Synonymous variants: 490 observed, 501.43 expected, observed/expected ratio (o/e) 0.98, 90% interval 0.91 to 1.05.
Homologues: Orthologues: chimpanzee ARHGAP20 (99% identical), macaque ARHGAP20 (98% identical), dog ARHGAP20 (87% identical), rabbit ARHGAP20 (86% identical), pig ARHGAP20 (82% identical), rat Arhgap20 (79% identical), mouse Arhgap20 (79% identical), guinea pig ARHGAP20 (68% identical), tropical clawed frog arhgap20 (44% identical), tropical clawed frog arhgap20b (29% identical), zebrafish arhgap20 (25% identical), Drosophila melanogaster RhoGAP71E (11% identical), and 2 more. Paralogues in human: TAGAP (14% identical).
Diseases named in the same sentence as ARHGAP20 in open-access papers:
ARHGAP20 is named in the same sentence as 14 diseases in open-access papers, as found by Europe PMC text mining. Sharing a sentence is not in itself a finding about the gene and the disease. The quoted sentences say what the papers report.
Obesity (2 papers, 2022). Accumulation of substantial excess body fat. "The FDX1/ARHGAP20 locus has been associated with renal sinus fat which has a proposed link between obesity and renal function." (PMID 35115544, 2022). "Seven of the genes were downregulated by obesity and reversed by VSG specific weight loss including Ido1, Aldoc, Tmem125, Dgki, Slc7a4, Msc, and Ephb3, while four were inversely regulated with obesity elevating Klhl5, Nek6, Arhgap20, and Hp." (PMID 35775614, 2022).
breast carcinoma (1 paper, 2025). "There is a number of scientific research for each of the top 10 mRNA genes, well-documenting their significance and association with cancerogenesis: ADAMTS5, TMEM220, ARHGAP20, MICU3; or precisely with breast cancer: COL10A1, MMP11, CAVIN2 (formerly known as SDPR), PLPP3, MME, and CD300LG." (PMID 40724805, 2025).
leukemia (1 paper, 2018). A malignant (clonal) hematologic disorder, involving hematopoietic stem cells and characterized by the presence of primitive or atypical myeloid or lymphoid cells in the bone marrow and the blood. "Finally, the lead intergenic SNP at 11q23.1 maps between C11orf53 and ARHGAP20, whereas the 10p12.31 region encompasses MLLT10 which has been linked to various leukemias, ovarian cancer, and meningioma." (PMID 30258056, 2018).
lung carcinoma (1 paper, 2020). "MYOCD, RSPO1 and ARHGAP20 have all been implicated in various cancers, including lung cancer." (PMID 32899298, 2020).
prostate carcinoma (1 paper, 2021). A carcinoma that arises from epithelial cells of the prostate gland. "Previous studies showed the methylation of ARHGAP20 is associated with prostate cancer, but the relation with gastrointestinal tumours is not clear." (PMID 33949771, 2021).
tumour (3 papers, 2021 to 2024). "CNN1 (log2FC = −3.885), ARHGAP20 (log2FC = −3.312), and MEG3 (log2FC = −2.612) were downregulated, whereas miR-330 (log2FC = 0.431) was upregulated in tumor samples compared to normal samples." (PMID 38240701, 2024). "The results showed that 5 proteins (ADAM23, ARHGAP20, ICOS, IRF4,MMRN1) were significantly different in tumour tissues compared with normal tissues." (PMID 33949771, 2021). "Remarkably, in the TCGA‐LGG and GTEx cohorts, a significant majority of the ARHGAP family genes, with the exception of ARHGAP15, ARHGAP20, ARHGAP24, and ARHGAP28, exhibited notable differential expression between tumour tissues and normal samples, as established through Wilcoxon test analysis." (PMID 39075640, 2024). "Finally, 19 prognostic genes were verified by GSE17536 and GSE17537 from GEO, and five genes (ADAM23, ARHGAP20, ICOS, IRF4,MMRN1) were significantly different in tumour tissues compared with normal tissues at the protein level." (PMID 33949771, 2021).
ARHGAP20 also shares sentences with these, for which no sentence is quoted: cancer (2 papers); adenocarcinoma (1); diabetic nephropathy (1); gastrointestinal tumours (1); glucose metabolism disorder (1); hypertrophic cardiomyopathy (1); multiple sclerosis (1); ovarian carcinoma (1).